FARS2 (phenylalanyl-tRNA synthetase 2, mitochondrial)
Description:
Is responsible for the charging of tRNA(Phe) with phenylalanine in mitochondrial translation. To a lesser extent, also catalyzes direct attachment of m-Tyr (an oxidized version of Phe) to tRNA(Phe), thereby opening the way for delivery of the misacylated tRNA to the ribosome and incorporation of ROS-damaged amino acid into proteins.
Synonyms: PheRS; FARS1; HSPC320; dJ236A3.1; mtPheRS; COXPD14; SPG77
Tractability: Small molecule: a structure with a bound ligand is known; it has a high-quality binding pocket; it belongs to a druggable protein family. PROTAC: ubiquitination databases record sites on it; its protein half-life has been measured; a small molecule that binds it is known.
Target class: Enzyme; Ligase
Gene: Protein-coding gene on chromosome 6 (5,261,044 to 5,829,192, forward strand). Ensembl gene ENSG00000145982.
Subcellular location: Mitochondrion matrix; Mitochondrion
Pathways (Reactome):
Metabolism of proteins: Mitochondrial tRNA aminoacylation
Gene Ontology:
Molecular function: phenylalanine-tRNA ligase activity; protein binding; tRNA binding; aminoacyl-tRNA ligase activity; ATP binding; nucleotide binding
Biological process: phenylalanyl-tRNA aminoacylation; tRNA processing; tRNA aminoacylation for protein translation; tRNA aminoacylation
Cellular component: mitochondrion; mitochondrial matrix; cytoplasm
Genetic constraint (gnomAD): Loss-of-function variants: 33 observed, 43.47 expected, observed/expected ratio (o/e) 0.76, 90% interval 0.57 to 1.01. The upper end of that interval is the gene's LOEUF score, 1.01, which puts it in group 4 of 6, group 1 being the genes least tolerant of losing a copy. Missense variants: 484 observed, 557.09 expected, observed/expected ratio (o/e) 0.87, 90% interval 0.81 to 0.94. Synonymous variants: 226 observed, 212.7 expected, observed/expected ratio (o/e) 1.06, 90% interval 0.95 to 1.19.
Gene-disease validity (ClinGen):
ClinGen rates the evidence that FARS2 causes each of these diseases.
mitochondrial disease (autosomal recessive): Definitive.
Leigh syndrome (autosomal recessive): Moderate. A progressive neurological disease defined by specific neuropathological features associating brainstem and basal ganglia lesions.
Homologues: Orthologues: macaque FARS2 (95% identical), chimpanzee FARS2 (95% identical), guinea pig FARS2 (86% identical), rat Fars2 (85% identical), mouse Fars2 (84% identical), pig FARS2 (82% identical), dog FARS2 (81% identical), rabbit FARS2 (79% identical), tropical clawed frog FARS2 (67% identical), zebrafish fars2 (64% identical), Drosophila melanogaster PheRS-m (25% identical), Caenorhabditis elegans fars-2 (23% identical). Paralogues in human: FDXACB1 (22% identical), FARSA (18% identical).